GRIN1 (glutamate ionotropic receptor NMDA type subunit 1)
Diseases named in the same sentence as GRIN1 in open-access papers (continued):
Sharing a sentence is not in itself a finding about the gene and the disease.
neurodevelopmental disorder (21 papers, 2013 to 2026). A behavioral and cognitive disorder with onset during the developmental period that involves impaired or aberrant development of intellectual, motor, or social functions. "Patient 2 carries a heterozygous de novo mutation in the GRIN1 gene, which is associated with neurodevelopmental disorders involving seizures." (PMID 37408271, 2023). "GRIN1 (encoding NMDAR subunit n-methyl-D-aspartate 1) gene has been shown to be closely associated with neurodevelopmental disorders, and its polymorphism has also been demonstrated as a potential biomarker for reducing the risk of PD in previous studies." (PMID 36733342, 2023). "We identified 48 variants in the M3 transmembrane helix across GRIN1, GRIN2A, and GRIN2B in 56 patients with neurological and/or neurodevelopmental disorders." (PMID 38538865, 2024). "Collectively, these findings highlight the centrality of MGE-expressed Grin1-signaling during synapse formation and connectivity, which when aberrantly expressed, can lead to neurodevelopmental disorders." (PMID 34630033, 2021). "Our findings expand the known phenotypes in the spectrum of GRIN1-related neurodevelopmental disorders, which is essential for accurate diagnosis and development of specific therapeutic strategies." (PMID 33062288, 2020). "This case expands our understanding of the known phenotypes of GRIN1-related neurodevelopmental disorders." (PMID 33062288, 2020). "A comprehensive molecular docking analysis was conducted to characterize the binding interactions between selected natural compounds and three pivotal protein targets implicated in neurodevelopmental disorders: CSNK2B (PDB ID 3EED), GRIN1 (PDB ID 5H8H), and MAPK1 (PDB ID 6SLG)." (PMID 41009441, 2025). "The identification of natural compounds with favorable binding properties to the GluN1 subunit, as demonstrated in our molecular docking studies, may provide new avenues for developing safer and more effective treatments for GRIN1-related neurodevelopmental disorders." (PMID 41009441, 2025).
tumor (18 papers, 2009 to 2025). "The differences between GRIN1 and tumor mutational load (TMB) and microsatellite instability (MSI) were statistically significant, while L1CAM was negatively connected with TMB and SEMA4F was positively correlated with MSI." (PMID 36212450, 2022). "The results demonstrated a preferential expression pattern of GRIN1 and GRIN2D (the encoding genes of NMDAR) in tumor cells, highlighting the tumor-specific properties of sarcosine." (PMID 40275333, 2025). "In fact, the obligatory NMDAR subunit GRIN1 was downregulated in tumor tissues based on the analysis of GEO database." (PMID 37553583, 2023). "Tumor-specific demethylation was found in GRIN1 (p = 0.005), MAGEA11 (p = 0.001), and MAGEA2 (p = 0.002)." (PMID 19305507, 2009). "Interestingly, some studies associate the deregulation of GRIN1 and other NMDA receptors with tumor formation." (PMID 31266445, 2019). "The findings imply that the genes CHRM2, GRIN1, L1CAM, and SEMA4F in EC have pro- or oncogenic effects as a result of the combined activity of several signaling pathways influencing tumor growth." (PMID 36212450, 2022). "The epigenetic reactivation of TKTL1, H19, MAGEA2, MAGEA3/6, MAGEA4, MAGEA11, GPR17, GRIN1, and C19ORF28, genes located at diverse chromosomal loci, occurs simultaneously in individual primary tumors from multiple tumor types." (PMID 19305507, 2009). "The calcium signaling pathway (hsa04020) contained 23 genes (p = 8.81 × 10−7), including key receptors such as SLC8A2, HTR2C, GRIN1, CACNA1I, and GRIN2B, which regulate intracellular calcium levels and tumor microenvironment dynamics via glutamate interactions." (PMID 40406701, 2025). "Ultimately, immunohistochemical assay results showed that GRIN1 was detected in normal tissue and not in the tumor specimens." (PMID 34840971, 2021). "For example, loss of chromosome 9q34 removes tumor suppresser genes TSC1 (an mTOR pathway inhibitor), NOTCH1 (a development and stemness regulator), and GRIN1 (a calcium regulating tumor suppressor)." (PMID 27391266, 2016).
cancer (14 papers, 2013 to 2025). A tumor composed of atypical neoplastic, often pleomorphic cells that invade other tissues. "Combined with our results and previous reports, we suspect that HTR6 and GRIN1 play important roles in cancer development and warrant further investigation." (PMID 40661182, 2025). "Moreover, nonsense mutations were detected in GRHL2, GRIN1, NOL9 and TTC21B, however only GRHL2 and GRIN1 were previously shown to be involved in cancer." (PMID 29854292, 2018).
neurological diseases (14 papers, 2013 to 2025). "Natural variations in the GRIN1 gene, responsible for encoding the essential GluN1 subunit of the NMDA receptor, are linked to significant neurological disorders." (PMID 40740189, 2025). "Dysfunction of Grin1, an NMDA receptor subunit, has been associated with several neurological disorders." (PMID 37965042, 2023). "In addition, there was some overlap in genetic targets associated with cognitive function and neurological disease (e.g., GRIA3 and GRIN1) in one study that analyzed 8–10 weeks male mice brain tissue 4 h after exposure to 0.1 or 2 Gy." (PMID 25147559, 2014).
psychiatric disorder (13 papers, 2013 to 2025). A disorder characterized by behavioral and/or psychological abnormalities, often accompanied by physical symptoms. "GRIN1 (NR1) encodes an essential subunit of NMDAR, and its downregulation was reported in the postmortem brains of patients with psychiatric disorders." (PMID 33875800, 2021). "Among them, NTRK2 and GRIN1 have been the long-studied genes in psychiatric disorders, and their downregulation in the postmortem brains of BD patients has been established." (PMID 33875800, 2021). "The development of next-generation DNA sequencing has given rise to unique data linking patient variants in GRIN1 and GRIN2 genes to neurological and psychiatric disorders." (PMID 29681796, 2018). "PRKCE interacts with several proteins encoded by genes of potential relevance to psychiatric disorders, including the glutamate decarboxylases (GAD1, GAD2), NMDA receptors (GRIN2D, GRIN1), and a metabotropic glutamate receptor (GRM5)." (PMID 23922650, 2013). "Grin1 and Tymp are signal transduction-related factors between neurons, and abnormal transcriptional regulation of Grin1 may be related to the course of neurological and psychiatric disorders." (PMID 39796522, 2024). "GRIN1 knockdown mice showed various behavioral alterations related to psychiatric disorders." (PMID 33875800, 2021). "Grin1Rgsc174/Grin1+ mice show a unique profile of abnormal behaviors and may represent a subpopulation of patients with these psychiatric disorders." (PMID 23688147, 2013).
movement disorder (7 papers, 2018 to 2025). Neurological conditions resulting in abnormal voluntary or involuntary movement, which may impact the speed, fluency, quality and ease of movement. "Most GRIN1-related movement disorders are caused by de novo LOF mutations that affect the trans-membrane domains of GluN1, which is a highly conserved region." (PMID 38921008, 2024). "The whole-exome sequencing analysis of patients found that GRIN1 mutations caused seizures and movement disorders." (PMID 34035826, 2021).
neurodegenerative disease (6 papers, 2014 to 2025). A disorder of the central nervous system characterized by gradual and progressive loss of neural tissue and neurologic function. "In the past decade, numerous studies have shown that GRIN1 dysfunction causes various neurodegenerative diseases and mental illness." (PMID 34840971, 2021).
GRIN1 also shares sentences with these, for which no sentence is quoted: Stroke (16 papers); autoimmune disease (8); alcohol dependence (6); autoimmune encephalitis (6); cognitive decline (6); autoimmune disorder (5); dementia (5); Cerebral ischemia (4); infection (4); memory impairment (4); ovarian teratoma (4); status epilepticus (4); alcohol (3); Dystonia (3); herpes simplex encephalitis (3); microcephaly (3); migraine (3); Seizure (3); anti-NMDA receptor encephalitis (2); Dyskinesia (2); generalized cerebral atrophy (2); generalized seizures (2); Hypertension (2); myotonic dystrophy type 1 (2); neuromyelitis optica (2); Orofacial dyskinesia (2); tauopathy (2); tendinopathy (2); teratoma (2); vascular dementia (2).
A further 89 diseases each share a sentence with GRIN1 in 2 papers or fewer.